IL1RL1 (interleukin 1 receptor like 1)
Diseases named in the same sentence as IL1RL1 in open-access papers (continued):
Sharing a sentence is not in itself a finding about the gene and the disease.
IL1RL1 also shares sentences with these, for which no sentence is quoted: Allergy (6 papers); rheumatoid arthritis (5); dermatitis (4); Alzheimer disease (3); diabetes mellitus (3); Hypertension (3); hypothyroidism (2); liver disease (2); liver fibrosis (2); parasitic infection (2); respiratory diseases (2); adenoma (1); alopecia areata (1); anemia (1); Behcet disease (1); chronic rhinosinusitis (1); congenital heart disease (1); coronary artery disorder (1); dialysis (1); dyslipidemia (1); eosinophilic esophagitis (1); familial Mediterranean fever (1); fungal infection (1); gestational diabetes mellitus (1); granulocytosis (1); hay fever (1); hyperlipidemia (1); ichthyosis (1); idiopathic inflammatory myopathies (1); ileitis (1).
A further 31 diseases each share a sentence with IL1RL1 in 1 paper.